ZEB2 (zinc finger E-box binding homeobox 2)
Diseases named in the same sentence as ZEB2 in open-access papers (continued):
Sharing a sentence is not in itself a finding about the gene and the disease.
glioma (continued). "qRT-PCR and Western blot showed that miR-192-5p overexpression markedly repressed ZEB2 expression at both mRNA and protein levels, whereas downregulating miR-192-5p increased ZEB2 expression in glioma cells." (PMID 36193069, 2022). "For example, miR-622 levels predict poor prognosis and it exhibits functions by targeting zinc finger E-box binding homeobox 2 (ZEB2) in glioma." (PMID 32677950, 2020). "miR-200b overexpression alleviates cell migration and EMT in glioma U251 and U87 cells by negatively regulating ZEB2 expression." (PMID 32149094, 2020). "Our findings are in agreement with published report whereby loss of NF1 by shRNA promoted glioma cell invasion and upregulation of EMT markers such as vimentin, SNAI, TWIST1, ZEB1, and ZEB2." (PMID 30967630, 2019). "Expression of ZEB1 and ZEB2 was significantly increased in glioma tissues compared with normal tissues." (PMID 31429770, 2019). "Here, the authors show that EphrinB2 expression is reduced in glioma cells both by genetic and epigenetic alterations and under hypoxia, through a HIF1α-mediated direct regulation of ZEB2, which enhances invasion and anti-angiogenic resistance." (PMID 27470974, 2016). "To this end, we analysed by immunofluorescence the expression of ZEB2 and ephrinB2 in the highly invasive glioma cell line LN229 following intracranial transplantation." (PMID 27470974, 2016). "Collectively our findings demonstrate that the ZEB2–ephrinB2 axis is a crucial regulator of tumour invasion in glioma, whose blockade can overcome evasive resistance following anti-angiogenic treatment." (PMID 27470974, 2016). "ZEB2 was highly upregulated in glioma cells at the tumour rim and invading the adjacent brain parenchyma." (PMID 27470974, 2016). "Functionally, hypoxia and overexpression of ZEB2 in human glioma cells repressed the activity of the ephrinB2 promoter as assessed by a luciferase reporter assay." (PMID 27470974, 2016). "To further corroborate the regulation of ephrinB2 expression by ZEB2 and hypoxia we silenced ZEB2 in the human glioma cell lines G55 and LN229." (PMID 27470974, 2016). "Collectively, these findings implicate ZEB2 activation and ephrinB2 downregulation as crucial steps in the invasion of gliomas." (PMID 27470974, 2016). "It is widely accepted that ZEB2 is involved in cancer invasion in different tumors, as glioma and renal cell carcinoma." (PMID 26136338, 2015). "The aim of the present study was to analyze the expression of Zinc finger E-box Binding homeobox 2 (ZEB2) in glioma and to explore the molecular mechanisms of ZEB2 that regulate cell proliferation, migration, invasion, and apoptosis." (PMID 22761708, 2012). "In agreement with a previous study, we found that knockdown of ZEB2 expression inhibited cell proliferation, migration, and invasion of glioma cells." (PMID 22761708, 2012). "To explore the role of ZEB2 in glioma we utilized two human cell lines established from high-grade tumors (U251 and U87 cells)." (PMID 22761708, 2012). "The changes of CDK4/6 and p21 mediated by ZEB2 knockdown in the U251 glioma cell line suggest potential avenues to target these proteins in tumors." (PMID 22761708, 2012). "Knockdown ZEB2 expression by siRNA suppressed cell proliferation, migration, invasion and promoted cell apoptosis in glioma cells." (PMID 22761708, 2012). "Expression levels and subcellular localization of ZEB2 protein was measured in 90 archived paraffin-embedded glioma samples and 10 normal brain tissues using immunohistochemical staining." (PMID 22761708, 2012).
glioma (continued). "To study the link between cell cycle control and ZEB2 in glioma cells, we first assessed the cell cycle distribution by flow cytometry at 48 hr post transfection between negative control or siZEB2 treated cells." (PMID 22761708, 2012). "In the present study, we firstly confirmed that ZEB2 mRNA levels were higher in glioma samples than that in normal brain tissues." (PMID 22761708, 2012). "Further, we found that ZEB2 was mainly localized in the nucleus and cytoplasm of glioma tissues while predominantly weakly expressed in cytoplasm in normal brain tissues by immunohistochemistry." (PMID 22761708, 2012). "Consistent with mRNA levels, ZEB2 protein expression was significantly elevated in glioma samples compared to normal brain tissues." (PMID 22761708, 2012). "The expression level of ZEB2 protein was significantly increased in glioma tissues compared to normal brain tissues (P<0.001)." (PMID 22761708, 2012). "Expression of ZEB2 in 90 clinicopathologically characterized glioma patients was analyzed by immunohistochemistry." (PMID 22761708, 2012). "Knockdown of ZEB2 by siRNA suppressed cell proliferation, migration and invasion, as well as induced cell apoptosis in glioma cells." (PMID 22761708, 2012). "ZEB2 was highly expressed in 65.6% (59/90) of glioma samples compared to only 20.0% (2/10) of normal brain samples, which was a statistically significant difference (P<0.001)." (PMID 22761708, 2012). "Additionally, miR-192 suppresses tumor growth in brain cancers, targeting RAB2A in glioblastoma multiforme, ZEB2 in glioma, and DHFR in medulloblastoma." (PMID 40087755, 2025). "NOTCH1, SOX2, TJP1/ZO1, ZEB1, and ZEB2 have higher expression in lower-grade glioma vs GBM." (PMID 40679044, 2025). "In gliomas, EMT may significantly affect susceptibility to chemotherapy, as increased ZEB1/ZEB2 and decreased E-cadherin expression levels were observed in TMZ-resistant glioma cells." (PMID 37239035, 2023). "Among them, ZEB family members, such as ZEB1 and ZEB2, i.e., zinc finger E-box binding homeobox proteins, are also important modulators of the molecular network in gliomas with a substantial impact on the proliferation, invasion and migration of tumourigenic cells." (PMID 37239035, 2023). "Moreover, circ_0000189 facilitates cell proliferation, migration, and invasion, as well as EMT process, and represses apoptosis through the miR-192-5p/ZEB2 axis, suggesting that it is a valuable candidate target for glioma treatment." (PMID 36193069, 2022). "In addition, down-regulation of ZEB2 resulted in G1/S cell-cycle arrest and more apoptosis in glioma cells." (PMID 35071748, 2022). "Some mechanisms for hypoxia-inducing EMT in gliomas have been recognized; for example, VEGF inhibitor therapy will activate c-Met and upregulate Snail and N-cadherin, and HIF-1α can upregulate Zeb2, which will downregulate EphrinB2, an invasion-inhibitory receptor in gliomas." (PMID 36338770, 2022). "Moreover, miR-769-3p inhibits tumor progression in glioma by suppressing ZEB2 and inhibiting the Wnt/β-catenin signaling pathway." (PMID 36139534, 2022). "circ_0000189 facilitates the progression of glioma by modulating miR-192-5p/ZEB2 axis." (PMID 36193069, 2022). "Additionally, the expressions of circ_0000189 and ZEB2 mRNA were positively correlated in glioma tissues." (PMID 36193069, 2022). "miR-769-3p and miR-590-3p repress glioma progression by repressing ZEB2." (PMID 36193069, 2022). "In conclusion, this study revealed a new MALAT1/mir-124/ZEB2 axis that was correlated with glioma progression and could be a new therapeutic target in glioma." (PMID 35071748, 2022). "Additionally, ZEB2 knockdown inhibited proliferation, migration, invasion, and increased cell death in glioma-derived cell cultures." (PMID 31429770, 2019). "Notably, our study highlights a function for ZEB2 in the acquisition of invasive traits, which is also activated to mediate evasive resistance to anti-angiogenic treatment in at least a subset of gliomas." (PMID 27470974, 2016).
glioma (continued). "In line with the pro-invasive function of a ZEB2-mediated ephrinB2 downregulation, we observed that ZEB2 was highly upregulated in tumour cells at the invasive front, whereas ephrinB2 expression was attenuated in infiltrating glioma cells." (PMID 27470974, 2016). "In summary, ZEB2 expression may have significant value as an unfavorable progression indicator for glioma patients." (PMID 22761708, 2012). "However, there is little knowledge of the relationship between ZEB2 and cell cycle progression or apoptosis in glioma cells." (PMID 22761708, 2012). "We hypothesize that ZEB2 regulates cell cycle progression, migration, invasion, and apoptosis in glioma through at least two molecular mechanisms." (PMID 22761708, 2012). "Furthermore, we also observed that the expression level of ZEB2 was positively correlated with tumor grading as there was a significant difference between high and low grade gliomas." (PMID 22761708, 2012). "ZEB2 regulation of cell growth has been reported through cell colony formation assays in glioma." (PMID 22761708, 2012). "Protein expression of ZEB2 between glioma and normal brain tissues." (PMID 22761708, 2012). "Elevated expression of ZEB2 is associated with degree of malignancy, rapid cell proliferation, and poor patient survival in different tumors, suggesting that ZEB2 expression may have significant value as a biomarker in glioma patients." (PMID 22761708, 2012). "Correlation between the clinicopathologic characteristics and expression of ZEB2 protein in glioma." (PMID 22761708, 2012). "In addition, high levels of ZEB2 protein were positively correlated with pathology grade classification (P = 0.024) of glioma patients." (PMID 22761708, 2012). "Furthermore, siRNA targeting ZEB2 was transfected into U251 and U87 glioma cell lines in vitro and proliferation, migration, invasion, and apoptosis were examined separately by MTT assay, Transwell chamber assay, flow cytometry, and western blot." (PMID 22761708, 2012). "However, we observed that the expression of ZEB2 was positively correlated with the status of pathology classification (WHO I-II vs. WHO III-IV) (P = 0.024) in glioma patients." (PMID 22761708, 2012). "ZEB2 may contribute to tumor progression by protecting cancer cells from apoptosis and DNA damage by activating NF-κB, which can prevent cell death in glioma and result in downregulation of E-cadherin mediated classical EMT." (PMID 22761708, 2012). "In addition, it has also been reported that targeted inhibition of ZEB2 induced upregulation of E-cadherin expression and downregulation of vimentin expression leading to reduced invasion and migration of pediatric glioma and adult glioma cells." (PMID 39941886, 2025). "However, the upstream mechanism contributing to ZEB2 dysregulation in glioma needs further study." (PMID 36193069, 2022). "We identify the ZEB2-mediated suppression of ephrinB2 as a central regulatory pathway in governing tumour invasion and resistance to anti-angiogenic therapies in glioma, suggesting a therapeutic target that could help counteract the development of evasive resistance." (PMID 27470974, 2016). "Overexpression of ZEB2 is an unfavorable factor that may facilitate glioma progression." (PMID 22761708, 2012). "Downregulation of the ZEB2 suppressor miR-622 correlated with advanced WHO pathological grade and low Karnofsky performance score (KPS) in 108 tissue samples obtained from glioma patients (Pearsons’s Chi-square test)." (PMID 37239035, 2023). "Through their interplay with ZEB1/ZEB2, they impact EMT-related pathways in gliomas, contributing to the proliferation, migration and invasion of tumourigenic cells." (PMID 37239035, 2023).
glioma (continued). "The ZEB proteins ZEB1 and ZEB2 are another notable family of transcription factors that mediate EMT in a variety of tumors, including gliomas." (PMID 35163279, 2022). "Western blot was utilized to evaluate ZEB2 expression and epithelial-mesenchymal transition (EMT-)-related proteins (E-cadherin, N-cadherin, as well as Vimentin) in glioma cells." (PMID 36193069, 2022). "In particular, miR-590-3p has also been found to be downregulated in glioma and impedes the malignant development of glioma cells through targeting ZEB1 and ZEB2." (PMID 31186064, 2019). "Here, we found that ING5 up-regulated the Claudin 1 expression, but down-regulated the expression of N-cadherin, Slug, Snail, Twist, Zeb1 and Zeb2, indicating that ING5 suppressed the EMT in glioma." (PMID 28915612, 2017). "Our study now unravels a parallel crucial mechanism on how VEGF inhibition promotes glioma invasion through the induction of HIF-1α and the EMT regulator ZEB2." (PMID 27470974, 2016). "Consistently, silencing of HIF-1α abrogated the hypoxic increase in ZEB2 protein levels, whereas overexpression of HIF-1α in normoxic human glioma cells was sufficient to increase the levels of ZEB2." (PMID 27470974, 2016). "KITENIN induced the expression of the epithelial-mesenchymal transition (EMT) markers (N-cadherin, ZEB1, ZEB2, SNAIL and SLUG) as well as the glioma stemness markers (CD133, ALDH1 and EPH-B1)." (PMID 25605251, 2015). "In our study, we demonstrated that high ZEB2 expression not only regulated EMT, but also mediated the cell cycle progression and apoptosis in glioma cell lines." (PMID 22761708, 2012). "For instance, in glioma cells lncRNA SNHG5 is bound directly to miR-205-5p, thus preventing the inhibition of its endogenous target, ZEB2; in another study, lncRNA HOTAIRM1 activated ZEB2 expression by repressing miR-873-5p (a tumour suppressor)." (PMID 37239035, 2023). "For example, lncRNA Linc00645 can regulate mesenchymal biomarker ZEB2 and induce EMT in glioma." (PMID 34485294, 2021). "Whereas ZEB1 and ZEB2 expression were highly expressed in low-grade, IDH-Mutant, 1p19q codel and younger glioma patients, indicating that the potential function of these genes in glioma malignancies." (PMID 32154177, 2020). "ZEB2 overexpression is characterized by a full-scale shift in phenotype indicative of EMT, and is involved in cell migration and invasion which are key steps in the progression of glioma." (PMID 22761708, 2012). "The results showed that the mRNA expression levels of Twist1, Twist2, Zeb1, Zeb2 and Slug2 maintained significantly negative correlations with the mRNA expression levels of Presenilin1 in gliomas of all WHO grades, but the relationships were not significant between Presenilin1 and Slug1." (PMID 34781973, 2021). "Interestingly, the expression levels of other significant cell cycle regulators including p27 and p16 did not change after ZEB2 knockdown which suggests similar regulatory effects on the cell cycle machinery mediated by ZEB2 in glioma cells." (PMID 22761708, 2012). "TCGA database analysis showed that ZEB1, ZEB2 and TWIST1 expression, but not E-Cadherin, were increased in glioma." (PMID 31429770, 2019).
hepatocellular carcinoma (42 papers, 2012 to 2025). A malignant tumor that arises from hepatocytes. "In in vitro studies with hepatoma cell lines, the transcription factor Zinc finger E-box binding homeobox 2 (ZEB2) bound to Cp, and the overexpression of ZEB2 led to a reduction in HBV transcripts and secreted proteins." (PMID 38793645, 2024). "ChIP-seq data have been published for high-Zeb2 hepatocellular carcinoma and leukemia cell lines, or cultured cells that overproduce an epitope-tagged Zeb2 (tag-Zeb2) from cDNA-containing episomal vectors or the safe-harbor Rosa26 locus." (PMID 36980900, 2023). "Lnc-ZEB2-19 was extremely downregulated in hepatocellular carcinoma tissues as well as in HCC cell lines." (PMID 37564197, 2023). "By binding to the 3 ́-untranslated region (3 ́-UTR) of target ZEB2 mRNA, miR-212 restored paclitaxel sensitivity in hepatocellular carcinoma cells." (PMID 35992812, 2022). "MiR-211-5p has been linked to short survival in hepatocellular carcinoma patients, and the restoration of miR-211-5p expression inhibited hepatocellular carcinoma cell proliferation, migration and invasion in vitro by targeting ZEB2." (PMID 33658048, 2021). "It is noteworthy that the invasion, EMT and metastasis of hepatocellular carcinoma can be decreased by FOXO1 via ZEB2." (PMID 34511023, 2021). "lncRNA-ATB is a classic example, which competitively binds miR-200s and upregulates miR-200s targets ZEB1 and ZEB2 in hepatocellular carcinoma." (PMID 34094894, 2020). "Initially we analysed ZEB1, ZEB2, E-cadherin and vimentin expression in eight Hepatoma-derived cell lines." (PMID 31543517, 2019). "It was also shown that miR-211 has important regulatory role in hepatocellular carcinoma metastasis by targeting zinc finger E-box-binding protein ZEB2." (PMID 31652435, 2019). "As an epithelial-mesenchymal transition (EMT) regulator, zinc finger E-box binding homeobox 2 (ZEB2) can promote vasculogenic mimicry form by hepatocellular carcinoma cells." (PMID 26747273, 2016). "Univariate analysis of ZEB2 expression and clinicopathologic variables in 248 patients with primary hepatocellular carcinoma (log-rank test)." (PMID 22393452, 2012). "The upregulation of TGF-β1 by ZEB2 has been elucidated in hepatocellular carcinoma." (PMID 40510028, 2025). "Additionally, TGF-β1, as a classic anti-inflammatory modulator, had been proved to be upregulated by ZEB2 in hepatocellular carcinoma according to previous research, so it was also included for further analysis." (PMID 40510028, 2025). "miR-211-5p may play an inhibitory role in hepatocellular carcinoma (HCC) by suppressing the expression of ZEB2." (PMID 40427372, 2025). "For instance, Huang’s team reported that SPOP could inhibit hepatoma cell migration, including the suppression of ZEB2 expression and the related program of epithelial–mesenchymal transition." (PMID 37941785, 2023). "Of them, lncRNA-ATB upregulated the zing finger E box-binding homeobox (ZEB1 and ZEB2), facilitating the EMT and driving distant metastasis in hepatocellular carcinoma." (PMID 39682098, 2024). "The lncRNA ATB has been reported to increase the expression of ZEB1 and ZEB2 by acting as ceRNA for the miR-200 family, inducing EMT in hepatocellular carcinoma cells." (PMID 36841801, 2023). "Only two studies present ZEB2 ChIP-seq data in human cells, i.e., SNU398 hepatocellular carcinoma and K562 erythroleukemia cells, respectively." (PMID 36980900, 2023). "For instance, lncRNA-ATB can induce epithelial-mesenchymal transition (EMT) to promote hepatocellular carcinoma (HCC) invasion by competitively binding miR-200 to upregulate ZEB1 and ZEB2." (PMID 34091587, 2021). "For example, ATB lncRNA blocked miR-200 family by binding to its targets and upregulated ZEB1 and ZEB2, thereby inducing EMT and invasion in hepatocellular carcinoma." (PMID 30181715, 2018).